FUT8 (fucosyltransferase 8)
Diseases named in the same sentence as FUT8 in open-access papers (continued):
Sharing a sentence is not in itself a finding about the gene and the disease.
cancer (76 papers, 2013 to 2026). A tumor composed of atypical neoplastic, often pleomorphic cells that invade other tissues. "Abnormal core fucosylation, which is mediated by FUT8, is frequently associated with the development of various cancers." (PMID 40770702, 2025). "E-calmodulin is considered a substrate for FUT8, and the core fucosylation of E-calmodulin is positively associated with cancer metastasis." (PMID 40373023, 2025). "For example, FUT8 regulates the cancer-promoting capacity of cancer-associated fibroblasts CAFs in NSCLC." (PMID 40373023, 2025). "Abnormal glycosylation is a hallmark of cancer cells, characterized by the disruption of core fucosylation, which is predominantly driven by the enzyme fucosyltransferase 8 (FUT8)." (PMID 40373023, 2025). "It is found that the deficiency of FUT8 can down-regulate the stemness of cancer cells and result in the decrease of the expression of corresponding biomarkers, such as CD133, EpCAM, and c-Met." (PMID 38277230, 2024). "Of interest in terms of its consistent high pan-cancer expression profile in both data sets is FUT8—notably the only enzyme-encoding gene known to directly mediate core fucosylation via N-linkages." (PMID 36961502, 2023). "Upregulated expression of FUT8 in cancer-associated fibroblasts promotes the construction of an invasive tumor microenvironment in NSCLC through the core fucosylation of EGFR." (PMID 37256139, 2023). "FUT8 regulates the cancer-promoting capacity of cancer-associated fibroblasts by modifying EGFR core fucosylation." (PMID 37256139, 2023). "FUT8 is overexpressed in many human cancers and has been found associated with multiple cancer-related processes." (PMID 35303925, 2022). "FUT8 mediated core fucosylation is an important post-translational modification, that has been linked to cancer cell invasion and metastasis." (PMID 33466384, 2021). "The α1-6 fucosyl transferase FUT8 adds fucose to the inner Asn-linked GlcNAc, and its state of activity plays an important role in the malignancy of cancer cells and metastatic potential." (PMID 34943050, 2021). "Studies showed that alterations in the expression of some glycosylation-associated genes have been correlated with cancer progress and applied as cancer diagnostic biomarkers such as FUT8." (PMID 34966741, 2021). "The N-glycosylation product Fut8 is involved in the expression of cancer biomarkers as well as in the treatment of cancer, and GnT-V is highly associated with cancer metastasis, whereas GnT-III is associated with cancer suppression." (PMID 33509226, 2021). "This review / meta-analysis is, to our knowledge, the first to comprehensively clarify the association of FUT8 expression with specific clinicopathological features and survival data for various types of cancer." (PMID 33323540, 2020). "Overexpression of FUT8 has been observed in several malignant tumors, which is linked to the severity of these cancers." (PMID 29339807, 2018). "In the current study, we report that the expression of Fut8 is significantly up-regulated in tumor tissues of patients with HCC, and the up-regulation of Fut8 is associated with poorly differentiated cancer in patients with HCC." (PMID 24927126, 2014). "FUT8, the sole enzyme to catalyse core fucosylation, has been implicated in various cancers." (PMID 38279874, 2024). "Increased FUT2 and FUT8 expression has been linked to cancer." (PMID 38456503, 2024). "FUT8 is associated with the maintenance of cancer cell stemness." (PMID 38277230, 2024). "Furthermore, a combination of data mining of FUT8 expression at the mRNA level and the analysis of three public microarray datasets revealed high FUT8 levels are associated with cancer cell invasiveness and poor prognosis." (PMID 33466384, 2021).
cancer (continued). "The nuclear β-catenin along with lymphoid enhancer binding factor 1 (LEF-1) activates FUT8 expression, causing FUT8 upregulation, globally altering core fucosylation, cancer cells’ response to extracellular matrix, growth factors, and other elements of the tumour microenvironment." (PMID 33466384, 2021). "In cancer, FUT8 promotes the immune escape, proliferation, and metastasis of tumors by altering the pattern of tumor-cell surface glycosylation, making it a potential target for anti-tumor immunotherapy." (PMID 40299448, 2025). "Numerous studies have shown that FUT8 is abnormally overexpressed in various cancer types, leading to malignant transformations such as proliferation, invasion, and metastasis." (PMID 40666289, 2025). "FUT8 is elevated in a variety of cancers, and affects tumor development and metastasis by regulating key molecules in the tumor microenvironment, such as B7-H3." (PMID 40373023, 2025). "Fucosyltransferase 8 (FUT8) is highly expressed in cancer cells, which is responsible for mediating the core fucosylation of the key immune checkpoint molecule, CD276 (B7-H3)." (PMID 40083922, 2025). "Targeting aberrant fucosylation holds huge potential for cancer research, and given the critical roles of FUT8 in tumour pathology, it is poised to be a druggable target for new cancer therapies." (PMID 40387385, 2025). "Evidence indicates that FUT8 is a pivotal enzyme in cancer onset and progression, influencing cellular glycosylation pathways." (PMID 40373023, 2025). "Altered core fucosylation mediated by FUT8 is a key change in tumour glycan patterns that contributes to cancer growth, metastasis, and immune evasion." (PMID 40387385, 2025). "FUT8 is considered to be an important therapeutic target in multiple malignancies that the knockout of FUT8 gene can significantly reduce the migration and proliferation of cancer cell." (PMID 40373023, 2025). "It is worth noting that the correlation of FUT8 with cellular functions varies across different cancers." (PMID 40729369, 2025). "What’s more, FUT8 inhibition can alleviate the cancer radioresistance and suppress the growth of tumor cell." (PMID 38277230, 2024). "Based on our data, it is evident that inhibition of FUT3 and FUT8 plays a significant role in the production and stability of CD15s and E-cadherin, which are important cancer cell markers." (PMID 38911244, 2024). "FUT8, which attenuates cancer aggressiveness when knocked down, is overexpressed at both the mRNA and protein levels in lung and colorectal cancer (CRC) samples and its expression is associated with poor prognosis." (PMID 39123480, 2024). "We found that FUT2, FUT3, and FUT8 exhibited significantly elevated expression levels in older patients with both cancers when compared with young patients." (PMID 38456503, 2024). "Cancer-associated upregulation of GMDS and FUT8 leads to an enhancement in core fucosylation followed by appearance of mesenchymal markers, indicating enhanced EMT." (PMID 39123480, 2024). "Fucosyltransferase 8 (FUT8) is a potential therapeutic target with high level in most malignant cancers including CRC." (PMID 37537172, 2023). "Given that many of the target N-glycoprotein scaffolds of FUT8-mediated fucosylation are secreted, we next asked whether the association between fucosylation gene expression and drug resistance is interrelated with expression changes in the components of the core cancer secretome (CCS)." (PMID 36961502, 2023). "Using IHC, we revealed that overexpression of circFUT8 led to upregulation of FUT8 protein in cancer tissues, while knockdown of circFUT8 showed the opposite effect." (PMID 37669906, 2023). "In some cancers, FUT8 expression is significantly higher than in paracancerous tissues or cells and affects cell invasion, metastasis, and drug resistance." (PMID 37196106, 2023).
cancer (continued). "RNAi silencing of FUT8 has been shown to reduce core-fucosylation of cancer cells and functionally inhibit their migration and invasion in vitro, as well as tumor growth capacity in vivo." (PMID 36980181, 2023). "Our results reported in this study confirm that the communication between cancer cells and antibody-secreting B cells results in the downregulation of the FUT8 gene and the level of the core fucose of the N-glycan in IgG in antibody-secreting B cells." (PMID 37865317, 2023). "High-degree pan-cancer expression of FUT8 and its activity in the Golgi entail the substrate specificity of FUT8 in fucosylating scaffolds in the secretory pathway." (PMID 36961502, 2023). "Fucosyltransferase 8 (Fut8), the enzyme responsible for core fucosylation, shows low expression in healthy liver and is markedly overexpressed in cancer." (PMID 37215580, 2023). "The data on 533 LUAD cases (533 cancer tissues and 59 normal lung tissues) with FUT8 expression was extracted from TCGA database." (PMID 35237113, 2022). "FUT8 is widely involved in a variety of life processes, including in the differential diagnosis of tumors, cancer, immune response, the regulation of gut microbiota, and cell adhesion." (PMID 36499043, 2022). "Recent studies have demonstrated an important role for fucosyltransferase 8 (FUT8) in carcinogenesis and cancer progression." (PMID 35237113, 2022). "Surprisingly, enzymes responsible for the biosynthesis of well-known cancer-associated structures, such as β1,6 branching (MGAT5), sialyl-Tn (ST6GALNAC1) sLex (FUT6), Sia6LacNAc (ST6GAL1), and core-fucosylation (FUT8) lack any relationship with survival." (PMID 33919332, 2021). "In support of this, FUT8 has been shown to be up-regulated during EMT in several cancers suggesting a positive feedback loop that promotes EMT and tumour development." (PMID 33466384, 2021). "Overexpression of FUT8 would also suppress PSA production by cancer cells and promote resistance to gefitinib-induced cell death." (PMID 34069262, 2021). "FUT8 promotes cancer cell invasiveness by remodelling the core fucosylation of the TGF-β receptor, as the presence of core fucose strongly affects the binding affinity of the TGF-β receptor and thus TGF-β induced epithelial-mesenchymal transformation (EMT)." (PMID 34359624, 2021). "More recent data indicate that FUT8 is involved in controlling the function of cancer cell membrane receptors." (PMID 34359624, 2021). "Meis1 and Fut8 gene, which are activated by Fli-1 and the LDB1 complex bound at their enhancer regions, encode two proteins, which have functions in different cancer." (PMID 33733070, 2021). "FUT8 plays a key role in immune evasion in cancer, and has shown promise as a potential therapeutic target to improve responses to immunotherapy." (PMID 33466384, 2021). "FUT8 is frequently upregulated in cancer, and plays a critical role in immune evasion, antibody-dependent cellular cytotoxicity (ADCC), and the regulation of TGF-β, EGF, α3β1 integrin and E-Cadherin." (PMID 33466384, 2021). "We collected as many relevant articles and microarray datasets as possible to assess the prognostic value of FUT8 expression in malignant tumors." (PMID 33323540, 2020). "In cancer, aberrantly elevated expression of FUT8 is correlated with poor clinical outcomes of non-small-cell lung cancer patients." (PMID 31936666, 2020). "Core fucosylation by FUT8 is involved in various physiological, as well as pathophysiological processes, including cancer biology." (PMID 32099910, 2020). "Increasing evidence supports the theory that core fucosylation by FUT8 influences cancer biology by regulating growth factor functions." (PMID 32099910, 2020). "Some investigators reported possible involvement of FUT8 in cancer adhesion, migration, invasion, and metastasis." (PMID 32099910, 2020).
cancer (continued). "Recently, increasing evidence has supported the crucial involvement of core fucosylation by FUT8 in carcinogenesis and cancer progression." (PMID 32099910, 2020). "FUT8 is clearly involved in tumor initiation and progression, and in various biological behaviors of cancer, including cell proliferation, apoptosis, migration, and metastasis." (PMID 33323540, 2020). "In the context of cancer cell responses to therapies, FUT8 has been reported to promote drug resistance." (PMID 31450600, 2019). "These genes related to the selected probes are mostly associated with cancer and LN metastasis, such as TP73, PDX1, FUT8, HOXD1, NMT1, and SEMA3E." (PMID 28951630, 2017). "According to the genomic locations, the 20 probes were associated to 39 genes including well-known cancer-related genes, such as TP73, PDX1, and FUT8." (PMID 28951630, 2017). "Core-fucosylation, which is catalyzed by α1,6-fucosyltransferase (Fut8) in mammalian tissues, plays multiple roles in cancer." (PMID 27895315, 2016). "A study that used oligonucleotide arrays to examine human colonic tissue showed that FUT8 was upregulated only in carcinoma tissue." (PMID 26539643, 2016). "FUT8 maintains high expression and protein stability of immune checkpoint molecules (including PD1, PDL1, PDL1 and B7H3) meaning there is a functional link between FUT8 activity and the suppressive state of the tumour microenvironment, and FUT8 is now a central target for cancer immunotherapy." (PMID 40387385, 2025). "FUT8 expression and activity are up-regulated in various human cancers." (PMID 40373023, 2025). "The results of the study demonstrated a significant reduction in the expression levels of fucosyltransferase 3 (FUT3) and fucosyltransferase 8 (FUT8) in both cancer stem-like cells and tumor tissues upon treatment with 2F-PerAcFuc, in comparison to the control groups." (PMID 38911244, 2024). "In addition, using publicly available microarray and RNA-seq data, we found that high expressions of FUK, SLC35C1, and FUT8 are generally correlated with poor first progression or relapse-free survival (RFS) in various cancer patient cohorts." (PMID 36961502, 2023). "MicroRNAs (miR) may play a role in the regulation of FUT8 gene, where miR-26a, miR-455-3p, miR-449a, and miR-34a can negatively regulate FUT8 expression in cancer cells." (PMID 36996026, 2023). "There are several mechanisms which could results in FUT8 upregulation in cancer among them implying microRNAs." (PMID 36699698, 2022). "Some of these FUT8 target proteins have been reported in other human cancers." (PMID 35303925, 2022). "Moreover, FUT8—as the only core fucosyltransferase—plays an important role in various physiological activities such as cancer, cell proliferation, migration, and immune and inflammatory responses in the body." (PMID 36499043, 2022). "It is with this newly provided information on the structure and enzymatic mechanism of FUT8 that the development of inhibitors could be developed for cancer therapy." (PMID 33466384, 2021). "Furthermore, FUT8 has been shown to be elevated at the protein level in metastatic cancer tissue in comparison to primary cancer tissue (n = 20)." (PMID 33466384, 2021). "Fucosyltransferase 8 (FUT8) is the sole enzyme responsible for core fucosylation, and aberrant fucosylation by dysregulated expression of fucosyltransferases is responsible for the growth of various types of carcinomas." (PMID 34857735, 2021). "We performed a systematic review and meta-analysis based on collection of references and Gene Expression Omnibus (GEO) microarray data, to clarify the correlations between FUT8 expression and clinical pathology and patient survival in various common types of cancer." (PMID 33323540, 2020). "Several investigators reported the involvement of FUT8 in the invasiveness of cancer cells." (PMID 32099910, 2020).
cancer (continued). "In particular, fucosyltransferase 8 (FUT8) is the only FUT responsible for α1, 6-linked fucosylation (core fucosylation), and it is involved in various physiological as well as pathophysiological processes, including cancer biology." (PMID 32099910, 2020). "Furthermore, the contributions of these FUT8-regulating mechanisms likely vary by pathological context, resulting in diversity of core fucosylation across cancers." (PMID 31450600, 2019). "Moreover, general analysis of FUT8 expression using data mined from TCGA showed a significant increase in FUT8 expression in cancer tissues compared to normal tissues." (PMID 31126011, 2019). "Importantly, FUT8 has been known to be upregulated in several types of human cancer, including HCC and CRC, and is known to be responsible for the synthesis of HCC-specific serum tumor marker, AFP-L3." (PMID 29975776, 2018). "Moreover, overexpression of FUT8 augments the activation of growth factor signaling pathways and thereby promotes cancer cell growth." (PMID 27977808, 2016). "FUT8 transcription has been reported to be regulated by several miRNAs in cancer cells." (PMID 27136596, 2016). "Increased expression of Fut8 has been shown in diverse carcinomas including hepatocarcinoma." (PMID 25652335, 2015). "Indeed, core fucosylation has been shown to promote EGFR receptor activation and downstream signalling and, moreover, it can influence the response to tyrosine kinase inhibitors, suggesting a potential relevant role of FUT8 in cancer treatment." (PMID 24130780, 2013). "Although the precise structural and functional basis underlying the upregulation of FUT8 during TGF-β-induced EMT still remains under investigation, the discovery of the regulatory mechanisms could unveil promising prognostic or therapeutic leads for cancers." (PMID 33466384, 2021). "Among these, the 35 datasets involved 7 types of malignant tumors and descriptions of 29 types of clinicopathological features related to FUT8, and the 7 articles involved 5 types of malignant tumors and described correlations between FUT8 expression and patient survival." (PMID 33323540, 2020). "The present findings and evidence obtained from examining other cancers lead us to speculate that FUT8 may be involved in the regulation of cancer proliferation, specifically in the rather differentiated portions characterized by an epithelial-like glandular structure." (PMID 32099910, 2020). "Importantly, as FUT8 is the only known fucosyltransferase to mediate core fucosylation, it might prove to be a valuable target for cancer therapy." (PMID 31450600, 2019). "However, FUT8 plays important roles in regulating cancer cell adhesion." (PMID 28706275, 2017). "Core fucosylation, catalyzed by fucosyltransferase 8 (FUT8), plays critical roles in cancer progression, immune evasion, and drug resistance, making it a compelling therapeutic target." (PMID 41667477, 2026). "The abnormal activity of FUT8 is elevated in tumor cell membrane glycoproteins, which may be related to cancer cell evasion from immune surveillance, the detection of FUT8 levels may serve as a biomarker for evaluating the prognosis and therapeutic response in cancer patients." (PMID 40373023, 2025). "Decoration (Core Fucosylation): the expression of fucosyltransferase 8 (FUT8) can increase invasion, proliferation, metastasis, and tumor growth in many different cancers." (PMID 34158025, 2021). "We first analyzed the expression of FUT8 at mRNA levels in a microarray dataset GSE41258, in which expression data for normal (n = 54) and cancer tissues (n = 186) were available." (PMID 29975776, 2018).